IL1B (interleukin 1 beta)
Diseases named in the same sentence as IL1B in open-access papers (continued):
Sharing a sentence is not in itself a finding about the gene and the disease.
schizophrenia (continued). "Contrary to many reports pointing to upregulated levels of IL-1β or IL-1Ra in schizophrenia, other studies found decreased or no significant alterations in the levels of these cytokines." (PMID 35163653, 2022). "IL-1β did not significantly change following treatment in schizophrenia (g: −0.25; CI −0.53 to 0.04; p = 0.086; I2 = 49%) and in MDD (g: −0.42; CI −1.40 to 0.55; p = 0.393; I2 = 88%)." (PMID 33653423, 2021). "In addition, IL-1β increases the expression of FOXP3 and CCL20 genes, the roles of which are also postulated in the etiopathogenesis of schizophrenia, more in patient astrocytes than in HC astrocytes." (PMID 34501305, 2021). "Other reports show a negative correlation between elevated levels of IL-1β mRNA (peripherally tested) and a reduced volume of Broca’s area and verbal fluency in schizophrenia." (PMID 34501305, 2021). "Studies on plasma cytokines levels have reported elevated levels of major inflammatory cytokines such as IL-1β, TNF-α, and INF-γ; low-grade systemic inflammation has been shown to be present in first-episode psychosis (FEP) and pre-onset state of schizophrenia." (PMID 33815179, 2021). "Studies have repeatedly (although not invariably) shown that patients with schizophrenia have increased serum concentrations of pro-inflammatory cytokines, including IL-1β, IL-6 and TNF-α." (PMID 30355368, 2019). "Secondly, both TNF-α and IL-1β showed moderately positive correlations with the PANSS negative subscore in the CP but not in FEDN patients with schizophrenia." (PMID 29867314, 2018). "We found significantly increased TNF-α and IL-1β levels in an immune-related animal model that imitated negative symptoms in schizophrenia in our recent study." (PMID 29867314, 2018). "In one sample, human IL-8 (and not IL-6, TNF-α, or IL-1β) was elevated in the serum of pregnant women whose offspring went on to develop schizophrenia and correlated with brain changes in the offspring." (PMID 30225350, 2018). "While longitudinal studies are needed to truly evaluate this hypothesis, the theory is consistent with findings that IL-1β as well as IL-6 and TGF-β may reflect state markers for schizophrenia." (PMID 29803226, 2018). "In this study, we did not reproduce our finding of upregulated peripheral IL-1β mRNA expression in the overall group of people with schizophrenia, previously reported in a subset of this cohort." (PMID 28923068, 2017). "They established that pro-inflammatory cytokine levels are constantly augmented in patients with schizophrenia and stated that pro-inflammatory cytokines like IL-6, IL-12, TNF-α, IL-1β, and IFN-γ are elevated in the blood and CSF in initial-onset and acute-relapse patients with schizophrenia." (PMID 27047333, 2016). "Pro-inflammatory cytokines such as tumor necrosis factor-α (TNF-α), IL-6, IL-1β, and interferon-γ (IFN-γ), formed by persistently actuated macrophages and T lymphocytes have also been conveyed as immunological altered components in schizophrenia." (PMID 27047333, 2016). "We also found that IL-6, SERPINA3 and IL-1β mRNA levels had significantly negative relationships with the volume reduction in schizophrenia, suggesting that increases in at least these three factors are linked to reduced brain volumes." (PMID 27959331, 2016). "An Ingenuity Pathway Analysis network indicates that these 4 molecules interact via IL1β, which shows a trend for differential expression in brain (p = 0.09) but not serum, and has previously been shown to be altered in schizophrenia CSF and serum." (PMID 23118852, 2012). "Since both the immunological background of drug resistance in patients with schizophrenia and the effects of ECT on cytokines have been insufficiently studied, we decided to examine immunology molecules such as IL-1β, IP-10, IL-17, IL-10, TNF-α, and sIL-2 receptor in TRS patients treated with ECT." (PMID 40364201, 2025).
schizophrenia (continued). "Earlier studies on both IL-1β and IL-17 suggested that these prominent cytokines may play a pivotal role in the etiology of schizophrenia, including TRS; however, this evidence is not conclusive." (PMID 40364201, 2025). "Furthermore, we report that, in patients diagnosed with pharmaco-resistant schizophrenia and treated with clozapine, the negative correlations between IL-1β-BDNF and between the FasL level and leukocyte count are absent." (PMID 41010622, 2025). "Furthermore, the resulting pro-inflammatory cytokine discharge, including interleukin-1β (IL-1β), IL-6, and TNF-α, and the disruption of the blood–brain barrier can collectively lead to the neurodevelopmental abnormalities characteristic of schizophrenia." (PMID 40806558, 2025). "Studies have shown that patients with schizophrenia exhibitelevated levels of monocytes, neutrophils, and C-reactive protein (CRP).Additionally, various cytokines (e.g., monocyte chemoattractant protein-1,IL-1β, IL-5, IL-6, IL-9 and TNF-α) have been reported to beupregulated in schizophrenia." (PMID 40926813, 2025). "Here, we analyzed changes in serum concentrations of cytokines (IL-1β, IL-2, IL-4, IL-6, IL-10, IL-21, APRIL, BAFF, PBEF/Visfatin, IFN-α, and TNF-α) and growth/neurotrophic factors (GM-CSF, NRG1-β1, NGF-β, and GDNF) in patients with schizophrenia in an exacerbation phase." (PMID 37239308, 2023). "However, there are a number of studies that describe the absence of changes in the concentrations of IL-1β in schizophrenia." (PMID 37239308, 2023). "Given that NF-κB kinases are necessary for forward propagation of the NF-κB signal from receptor to nucleus, it may appear counterintuitive that a subset of people with schizophrenia had downregulated peripheral expression of IKKβ and NIK transcripts but increased expression of IL-1β mRNA and CRP." (PMID 35027554, 2022). "This study suggests that elevated peripheral levels of TGF-β, but not IL-6, IL-1β, TNF-α, IFN-γ or IL-10, may not only predispose one to the development of schizophrenia, but may also be a consequence of childhood trauma." (PMID 34501305, 2021). "Concerning schizophrenia, a meta-analysis reported increased levels of IFN-γ, IL-1RA, IL-1β, IL-6, IL-8, IL-12, sIL-2R, TGF-β and TNF-α in acutely ill patients (i.e. acutely psychotic) with chronic schizophrenia and a significant decrease in IL-1β, IL-4 and IL-6 following treatment." (PMID 34584171, 2021). "The combination of selected cytokines (sIL2—increased by antipsychotics, and IL-1β and IFN-γ—decreased by antipsychotics) could be used as marker of the treatment response, since antipsychotic treatment corrected the inflammation in schizophrenia." (PMID 28358316, 2017). "Furthermore, we detected elevated expression of GFAP, a gliogenic (astrocyte) marker, in postmortem brains from schizophrenia patients without the 22q11.2 deletion, whereas inflammation markers (IL1B and IL6) remained unchanged." (PMID 27801899, 2016). "Thus schizophrenia patients taking haloperidol may be protected from RA onset by the suppression of TNF‐α and IL1‐β levels." (PMID 25656077, 2015). "Finally, we detected miR-3653-3p and NLRP3, Caspase 1 and IL-1β mRNA and explored the relationship between miR-3653-3p and NLRP3, Caspase 1, IL-1β in peripheral blood of schizophrenia; we look forward to searching for stable biomarkers of schizophrenia in peripheral blood." (PMID 37946206, 2023). "Moreover, we have shown that stratifying patients based on levels of IL-1β mRNA and CRP in the blood reveals some aspects of NF-κB dysregulation that are common to all people with schizophrenia and others that are unique to people with schizophrenia with inflammation." (PMID 35027554, 2022). "Though this may suggest that IL-1β and IFN-γ mRNAs increases in schizophrenia are mild to moderate, we would argue that large changes would not necessarily be expected in vivo in medicated patients with schizophrenia who appear to have low-level, subclinical inflammation." (PMID 35027554, 2022).
schizophrenia (continued). "Increased levels of pro-inflammatory cytokines such as interleukin (IL)-1β and tumor necrosis factor (TNF)-α have been found in the cerebrospinal fluid of schizophrenia patients, particularly those with negative symptoms." (PMID 39716387, 2024). "The IL1B/Il1b, IL6/Il6, or TNF/Tnf was not significantly upregulated in the schizophrenia postmortem brain sample and in the poly‐I:C model mice." (PMID 31657521, 2019). "But until now, no study has simultaneously reported TNF-α and IL-1β in both first-episode drug-naïve (FEDN) and chronic patients (CP) with schizophrenia." (PMID 29867314, 2018). "Elevations of IL-1β, IL-6, IL-8, IL-4, and TNF-α may also exacerbate negative symptoms of schizophrenia, whereas IL-6, together with IL-13 and IL-17, may intensify general symptoms in chronic schizophrenia." (PMID 40364201, 2025). "Furthermore, there is no significant increase in IL-1β levels in chronic patients, and there are diminished IL-1β and TNF-α levels in first-episode schizophrenia with a disease duration of less than 2 years." (PMID 36556337, 2022). "Two more studies reported that IL-1β and IL-1 receptor serum levels of MDD, BPD, and schizophrenia patients are not statistically different from those of healthy controls, although tissue studies revealed increased levels of IL-1β and IL-1 receptor in the frontal cortex of BPD patients." (PMID 32848904, 2020). "Thus, our study results also indicated that miR-3653-3p could be involved in the expression of NLRP3, caspase 1, and IL-1β, though NLRP3 was not statistically different between patients with schizophrenia and the controls." (PMID 37946206, 2023).
endotoxemia (162 papers, 2007 to 2026). "In this study, serum TNF-α, IL-1β, and IL-6 levels were remarkably elevated in the alcohol group, indicating that alcohol intake caused enteric-derived endotoxemia and produced large numbers of inflammatory factors." (PMID 37432394, 2023). "In a sublethal endotoxemia model, C5 was shown to cause significantly increased LPS-induced production of the proinflammatory cytokine IL-1β." (PMID 34943212, 2021). "Overall, these data indicate that well tolerated mannose administration regimen offers protection from experimental lethal endotoxemia, associated with decreased systemic IL-1β release." (PMID 33311467, 2020). "In conclusion, we document the beneficial effect of mTORC1-S6K suppression in an animal model of endotoxemia, associated with down-regulation of several cytokines, including IL-1β and VEGF, thought to be important in acute inflammatory response." (PMID 21200439, 2010). "Thus, this 43% reduction in plasma IL-1β detected during LPS-induced endotoxemia—attributable to a loss of C5aR1 signaling—strongly suggested that C5a engages C5aR1 in vivo to amplify TLR4-mediated IL-1β production in the endotoxemia model." (PMID 27382187, 2016). "Intravenous administration of either TNF-α or IL-1β can induce a similar change to that caused by endotoxemia and endotoxic shock, and cardiovascular abnormalities, and mortality can be ameliorated by applying IL-1β receptor antagonist or anti-TNF-α antibodies." (PMID 25209241, 2014). "Thus, the in vivo observations show that preservation of plasma Eh Cys/CySS during endotoxemia is associated with a decrease in IL-1β levels." (PMID 19325908, 2009). "In a rat endotoxemia model, fluoxetine treatment protected from elevated circulating levels of the pro-inflammatory cytokines tumor necrosis factor–α (TNFα), IL-6, and IL-1β." (PMID 39951524, 2025). "The effects of endotoxemia on the hypoxic mouse brain have been reported to induce exacerbation of inflammatory mediators IL-1β, IL-6, and TNF-α." (PMID 39940901, 2025). "Both, UDCA and CDCA pretreatment given orally for 10 days exerted anti-inflammatory effects manifested by a significant decrease in the levels of TNF-α, GM-CSF, and IL-1β in the LPS-induced endotoxemia." (PMID 38578526, 2025). "Compared with the null AAV9 vector, the endothelium-specific Gsdmd shRNA-knockdown AAV9 vector significantly improved the survival of the mice from 10% to 80% and decreased the release of IL-1β during endotoxemia." (PMID 39927458, 2025). "UK5099 effectively suppresses NLRP3‐mediated IL‐1β production in both mouse and human primary macrophages in vitro, as well as in an LPS‐induced endotoxemia model in mice in vivo." (PMID 38946607, 2024). "In particular, an intraperitoneal LPS injection in huNSG-QUAD mice resulted in similar serum levels of human TNF, IL-6, IL-8 and IL-1β in an analogous systemic endotoxemia experiment." (PMID 39399507, 2024). "When endotoxemia causes ALI, pro-inflammatory cytokines such as IL-1β and TNF-α are expressed by the neutrophils that migrate into the airways and infiltrate the lungs." (PMID 40007534, 2024). "Cmtm3 KO alleviated the release of TNF-α, IL-1β, and IL-10 in the peripheral blood of LPS-induced endotoxemia mice, while TLR4 overexpression reversed this alleviating effect." (PMID 39455728, 2024). "Further, a single dose of UK5099 persistently reduces IL‐1β production in an endotoxemia mouse model." (PMID 38946607, 2024). "As shown, IL-1β levels were largely dependent on NLRP3 activation in the LPS-induced endotoxemia model, as IL-1β was substantially reduced in NLRP3-KO control mice, regardless of pharmacological treatment." (PMID 37698938, 2023). "Most important, low doses of PLK1 kinase inhibitor markedly reduced IL-1β level in both LPS-induced endotoxemia and monosodium urate–induced (MSU-induced) peritonitis models in vivo." (PMID 37698938, 2023).
endotoxemia (continued). "Treatment with a selective PLK1 kinase inhibitor suppressed IL-1β production in in vivo inflammatory models, including LPS-induced endotoxemia and monosodium urate–induced peritonitis in mice." (PMID 37698938, 2023). "Serum and peritoneal IL-1β and IL-6 were also reduced by OI treatment of a murine model of lethal endotoxemia and peritonitis." (PMID 38085578, 2023). "Endotoxemia was assessed by measuringLBP andproinflammatory cytokine IL-1β in serum.Exposure to arsenate increased serum LBP levels relative to controlanimals at 15 and 30 mg/L As(V) concentrations (35–36%)." (PMID 37819996, 2023). "This is thought to be due to endotoxemia, damage associated molecular patterns (DAMPs) and induction of procalcitonin synthesis by TNF-α and IL-1β." (PMID 38435410, 2023). "The inflammatory response to LPS was validated by the substantial increments in circulating TNFα and IL-1β, two key proinflammatory cytokines that characterize the early immune response to endotoxemia." (PMID 37180728, 2023). "As the early mediators of endotoxemia, IL-1β and TNFα mainly released by macrophages from the injured site into circulation cause septic shock and multiple organ injuries." (PMID 36776867, 2023). "Gelam honey also improved survival and inhibited the production of pro-inflammatory cytokines (TNF-a and IL-1β) and oxidative stress in an in vivo model of LPS-induced endotoxemia in rats." (PMID 36557628, 2022). "Treatment with terrein increased the survival of mice and decreased the production of inflammatory cytokines, including interleukin-1β (IL-1β) and interleukin-6 (IL-6) in an LPS-induced endotoxemia model." (PMID 36422559, 2022). "In rats with endotoxemia, high levels of IL-6 and IL-1β reduced the mRNA expression levels of P-gp and MRP-2 in intestinal tissues." (PMID 36246609, 2022). "One study found that taVNS inhibited the expression of TNF-α, IL-1β, IL-6, and NF-kB p65 in endotoxemia rat serum through α7nAChR-mediated CAP." (PMID 36299906, 2022). "With the novel peptide KCF18, this study managed to achieve simultaneous inhibitions of TNF-α, IL-1β, and IL-6 and thus can compare the therapeutic effects of triple versus single cytokine inhibitions against endotoxemia." (PMID 35337084, 2022). "In summary, the results presented in this report demonstrated that terrein inhibits LPS-induced endotoxemia in mice and decreased levels of IL-1β and IL-6 in serum and lungs were observed in terrein-treated mice." (PMID 36422559, 2022). "At last, we found that the level of IL-1β in the serum was significantly decreased by treatment with 1,2-diol in endotoxemia mice." (PMID 35222388, 2022). "TNF-α and IL-1β, majorly secreted by macrophages, were recognized as essential initiators in endotoxemia shock." (PMID 35252164, 2022). "This lipopolysaccharide-induced endotoxemia in rats model showed that there was IL-1β induced downregulation of MRP-2 in enterocytes." (PMID 36246609, 2022). "Zn supplementation prevented the release of TNF-α and IL-1β, alleviated intestinal permeability and endotoxemia, reduced bacterial translocation, and inhibited changes in pathogenic intestinal flora in rats with SAP." (PMID 34400875, 2021). "For animals resuscitated with PolyHSA, serum TNF-α and IL-1β levels were significantly lower compared to animals resuscitated with HSA 24 h after LPS induced endotoxemia." (PMID 34035380, 2021). "Alcohol and corticosterone-induced endotoxemia were accompanied by a synergistic elevation of plasma TNFα, IL-1β, IL-6, and MCP1." (PMID 33436875, 2021). "In conclusion, the KCF18 peptide–based simultaneous inhibition of TNF-α, IL-1β, and IL-6 can alleviate liver injury in mice with endotoxemia." (PMID 34065201, 2021). "Endotoxemia-induced lung edema, neutrophil accumulation, nuclear translocation of NF-κB and production of proinflammatory cytokines (IL-1β and TNF-α) in lung neutrophils are reduced in transgenic mice lacking the catalytic subunit of PI3Kγ." (PMID 33821232, 2021).